STAT3 (signal transducer and activator of transcription 3)
Diseases named in the same sentence as STAT3 in open-access papers (continued):
Sharing a sentence is not in itself a finding about the gene and the disease.
tumor (continued). "Bacterial infection can cause the release of reactive oxygen species (ROS) which further activate multiple signaling pathways involving in tumor development, e.g., nuclear factor κB (NF-κB) and signal transducer and activator of transcription 3 (STAT3)." (PMID 38035341, 2023). "CD44 also facilitates tumor angiogenesis, immunosuppression, and metabolic reprogramming through interactions with STAT3, thereby supporting the pro-tumorigenic tumor microenvironment." (PMID 37284314, 2023). "STAT3, as a member of the STATs family, has a highly complex regulatory bioactivity and can exert pro-tumor, pro-inflammatory or anti-inflammatory and tissue repair effects through the activation of ligands such as IL-6/IL-10." (PMID 37081874, 2023). "In conclusion, the findings of this study demonstrated that STK24-mediated tumorigenesis, and tumor angiogenesis was dependent on STAT3/VEGFA signaling pathway." (PMID 36720310, 2023). "Excessive activation of STAT3 affects many tumor-related processes, including cell proliferation, survival, inflammation, invasion, metastasis, and angiogenesis." (PMID 38067351, 2023). "The high expression of EGFRvIII influenced by IL-6 promoted the proliferation of tumor cells in vitro, and IL-6 significantly influenced the expression of Bcl-XL and STAT3 in another tumor." (PMID 38201528, 2023). "The presence of ROR1 and pSTAT3 in both epithelial cancer cells and stromal cells clearly indicates that ROR1/STAT3 signaling sustains the OC tumor microenvironment." (PMID 37400436, 2023). "STAT3, as an oncogenic gene, acts on an extensive range of cell types, including tumour cells and immune cells." (PMID 36522474, 2023). "The ability of exosome biogenesis in different human cancer cells is positively correlated with the activation of STAT3/PKM2/SNAP23 pathway, and STAT3 plays a key role in regulating the biogenesis of tumor-derived exosomes." (PMID 37700835, 2023). "Accordingly, IL-17A/F secreted by pathogenic Th17 cells has been shown to contribute to the growth and metastasis of numerous cancers via increased secretion of IL-6 by tumor cells and tumor-stromal cells, resulting in Stat-3 activation." (PMID 37296927, 2023). "The JAK2 signaling transduction pathway phosphorylates STAT3, triggering the activation of pathways related to the production of chemokines released in the tumor microenvironment, promoting the attraction of macrophages." (PMID 37628945, 2023). "The flavonoid combined with paclitaxel can substantially decrease the amount of phosphorylated STAT3 in MB-231 cells, resulting in the tumor’s shrinking." (PMID 37958980, 2023). "Tocilizumab impaired the tumor progression of anlotinib-resistant OS cells, and combined treatment with anlotinib augmented these effects by inhibiting STAT3 expressions." (PMID 37404767, 2023). "Among them, the JAK2/STAT3 pathway is a component of JAK/STAT signaling that is upregulated in a variety of tumor cells and is particularly involved in the development of some solid tumors through the regulation of tumor cell proliferation and apoptosis." (PMID 37063281, 2023). "The transcription factor STAT3 exerts important effects on tumorigenesis and tumor-related inflammations." (PMID 37860678, 2023). "Inhibiting STAT3 activation in tumor cells triggers macrophage production of NO and leads to macrophage-mediated, nitrite-dependent cytostatic activity against tumor cells." (PMID 38001876, 2023). "Additional research has shown that arctiin is able to suppress inflammation, fibrosis, and the migration of tumor cells by inhibiting STAT3, TGF-β1, TLR4, NLRP3, VEGF, and cyclin D1." (PMID 37701157, 2023). "IL-6, made from T cells, macrophages, and fibroblasts in the tumor microenvironment, stimulates signal transducer and activator of transcription 3 (STAT3) signaling that contributes to tumor progression." (PMID 37432606, 2023).
tumor (continued). "In summation, these comprehensive results underscored that PRMT6-mediated tumor cell metastasis indeed hinges on STAT3 activation." (PMID 37813837, 2023). "High levels of STAT-3 in the tumour microenvironment, especially expressed by monocyte/macrophage cells, result in a poorer prognosis, i.e., promote an immunosuppressive phenotype." (PMID 37761018, 2023). "Many investigations have indicated that STAT3 is constitutively activated in many cancers and played a main role in tumor growth and metastasis." (PMID 37038114, 2023). "STAT3 is mainly involved in multiple effects cell growth, differentiation, and apoptosis; regulation of the immune response and tumor occurrence and metastasis; regulation of tumorigenesis; and regulation of cancer stem cells (CSCs)." (PMID 37372319, 2023). "IL6-activated STAT3 acts on the promoter of the B7-H4 gene and enhances the expression of B7-H4 on TAMs, which is an essential pro-tumor step of blocking effective T-cell immune responses." (PMID 37012233, 2023). "The possible mechanism is that TSN can directly bind to the SH2 structural domain of STAT3, inhibit the activation of STAT3 phosphorylation, and reduce p-STAT3 expression levels to inhibit tumor cell proliferation." (PMID 37946196, 2023). "Paxillin deficiency leads to the mislocalization of Src-activated STAT3, while STAT3 activity upregulates VEGF expression to promote tumor angiogenesis." (PMID 37175948, 2023). "For instance, the pro-inflammatory cytokine IL-6 stimulated the expression of Twist1 in normal fibroblasts, leading to their transdifferentiation into CAFs through STAT3 phosphorylation, thereby facilitating tumour invasion." (PMID 38173726, 2023). "n-Butanol extract of Huaier can inhibit the syntenin/STAT3 signaling pathway to inhibit tumor growth and metastasis." (PMID 37251326, 2023). "In MG-63 xenograft mice, curcumin decreases tumor size and p-JAK2 and STAT3 expressions, further validating tumor growth suppression through the JAK2/STAT3 pathway." (PMID 36923933, 2023). "Specifically, breast, ovarian, pancreatic, and nasopharyngeal cancers, have demonstrated that LIF overexpression by tumours contributes to tumor growth and metastasis as mediated by the STAT3 pathway." (PMID 37033980, 2023). "The JAK2/STAT3 axis is activated in human GC tissues, and JAK2/STAT3 signaling activation exerts a role in tumor growth and metastasis." (PMID 36814203, 2023). "Excessive IL-22 in the cancer microenvironment leads to tumor growth with the activation of the STAT3 pathway, and the epigenetic activation of genes with a STAT3-dependent pathway maintains the CRC stem cells." (PMID 37176567, 2023). "Multiple studies have demonstrated that STAT3 plays a crucial role in regulating various target genes during tumor development and progression, including VEGF, cyclin D1, and Bcl-xL." (PMID 37701157, 2023). "On the other hand, inactivated STAT3 in hematopoietic stem cells shows an anti-tumor effect, inhibiting tumor growth and metastasis by affecting the activation of DC, T, and NK cells." (PMID 36911202, 2023). "STAT3 is activated via the phosphorylation of STAT3 at Serine 727 (pSer727‐STAT3) and is subsequently localized into mitochondria and promotes mitochondrial respiration, which in turn drives tumor growth." (PMID 37334274, 2023). "Hypoxia within TME due to impaired blood vessels and greater usage of oxygen by tumour cells results in the activation of the immunosuppressive STAT3 pathway." (PMID 37686020, 2023). "Several cell types within the TME release IL-6, activating JAK/STAT3 signaling in both tumor cells and immune cells infiltrating the tumor, promoting tumor-cell proliferation, survival, invasiveness and metastasis." (PMID 37033251, 2023). "In OC, IL6 can activate the JAK/STAT3 signaling pathway, leading to tumor growth, metastasis, and EMT." (PMID 37445860, 2023).
tumor (continued). "Targeted sequencing of 180 genes in 11 cases identified highly recurrent activating STAT3 mutations and recurrent deletions of 1p22 involving RPL5, a tumor suppressor that regulates cell proliferation." (PMID 37810974, 2023). "STAT3 is a tumor promoter that helps tumor cells evade natural killer cell-mediated immune surveillance, and KLF5 is also associated with it." (PMID 36761967, 2023). "Signal transducer and activator of transcription 3 (STAT3) modulates chronic inflammation in tumor formulation and mediates interactions between tumor cells and stromal cells." (PMID 37765047, 2023). "STAT3 from tumor cells and myeloid cells is also known to induce IL-23 production by tumor associated macrophages; regulatory T cells expressing IL-23R are then activated to create an immunosuppressive tumor microenvironment." (PMID 37772080, 2023). "Butein-mediated inhibition of STAT3 phosphorylation as well as increased nuclear FoxO3a were observed in mouse tumor tissues." (PMID 37047012, 2023). "In this study, we found that tumor-bearing WT mice treated with a STAT3 inhibitor showed a reduction in the proportion of CD11b+Gr-1+ MDSCs (including M-MDSCs and G-MDSCs) and an increase in the proportion of CD11b+CD11c+ and CD3+ cells." (PMID 37308559, 2023). "In our prior bulk microarray analysis, we showed enrichment of the IL-6/STAT3 pathway in EPN tumor flow-sorted myeloid cells." (PMID 37694144, 2023). "An in vivo demonstration of DHME-induced retardation of CRC tumor growth and reduction in tyrosine 705 phosphorylation of STAT3 within CRC tumors is fundamental to underpinning DHME’s potential as a therapeutic option for CRC treatment." (PMID 37760971, 2023). "The data has shown that STAT3 phosphorylation and total STAT3 expression are dose-dependently decreased in Stattic-treating proliferating tumor cells." (PMID 37821959, 2023). "Signal Transducer and Activator of Transcription 3 (STAT3) is one of the key downstream signaling mediators of activated EGFR, which was proved to be associated with tumor angiogenesis, cell proliferation, and chemo-resistance." (PMID 36740689, 2023). "Many other molecular events are modulated by STAT3, and thus, it forms an ideal target molecule for the anti-tumor action of curcumin." (PMID 37765192, 2023). "Inhibiting the expression of p-STAT3, which is the phosphorylated form of STAT3, can induce apoptosis in tumor cells." (PMID 37946196, 2023). "Analysis of tumor sizes showed that STAT3 silencing inhibited the sizes of liver tumors during tumor formation." (PMID 36656267, 2023). "Subsequently, we evaluated the expressions of proliferation marker Ki67, METTL3 and STAT3 in tumor tissues by IHC staining and Western blotting assay." (PMID 37231451, 2023). "The tumor cell educates fibroblasts to construct tumor‐supported host matrix through STAT3 signal and c‐Jun N‐terminal kinase signal pathway, promotes ECM degradation and reconstruction, and stimulates PMN formation." (PMID 37902101, 2023). "In our previous study, we revealed that deactivation of STING signaling in tumor cells increases p-STAT3 signaling, resulting in interleukin-6 (IL-6) and IL-1β production in the tumor microenvironment." (PMID 36622166, 2023). "As a member of IL6 family, IL11 is known to promote tumor proliferation and metastasis mainly through activating STAT3 signaling." (PMID 37365574, 2023). "Among the factors driving increased STAT3 phosphorylation are mutations activating upstream tyrosine kinases or the increased presence of cytokines in a tumor microenvironment that can activate STAT3, produced through either autocrine or paracrine mechanisms." (PMID 38022653, 2023). "Macrophages activate STAT3 in tumor cells by expressing IL-6, thereby enhancing the proliferation and survival of malignant cells even during chemotherapeutic treatment." (PMID 36757936, 2023).
tumor (continued). "Active STAT3 promotes tumor cell proliferation, angiogenesis, immunosuppression, and tumor invasion; all of these factors create a pro-carcinogenic microenvironment and facilitate inflammation." (PMID 37371647, 2023). "For example, interleukin 6 (IL-6) is an important STAT3 activator and a major mediator of inflammation that acts on tumor cells to induce the expression of STAT3 target genes." (PMID 37242454, 2023). "In particular, NF-κB is overexpressed in multiple human cancers and activated STAT3 in tumor also induce IL-6." (PMID 37853413, 2023). "HRS cells expressed IL‐6, which exerted as autocrine or paracrine to promote tumor cell growth by triggering the activation of JAK/STAT3 signaling, which was essential for the development of cHL." (PMID 38020717, 2023). "Cause CD8+ T cell exclusion, tumor progression, and immunotherapy resistance via the IL35/gp130/STAT3 pathway." (PMID 37868967, 2023). "We found that IL-6 induced both STAT3 activation and tumor proliferation in SBC-3 and SBC-5 cells using western blotting analysis and a WST-8 assay." (PMID 36961655, 2023). "TNBC patients with high stromal STAT3 had reduced CD4+ T‐cell infiltrates within the tumour (p = 0.001) and higher tumour budding (p = 0.003)." (PMID 37199043, 2023). "STAT3 regulates the secretion of cytokines by tumor cells in addition to the cell cycle process and apoptosis." (PMID 38031104, 2023). "Hypoxia myeloid cells exhibit an MDSC phenotype with features including activation of STAT3 pathway, likely in response to tumor-secreted IL-6." (PMID 37694144, 2023). "Consistent with the literature, we observed that UA downregulated elevated IL-6, IL-1β, and TNF-α levels in the serum of LLC tumor-bearing mice and inhibited elevated phosphorylation of NF-κB and STAT3." (PMID 37190306, 2023). "More recently, the scientific literature has been filled with evidence showing that inhibiting constitutive STAT3 signaling effectively prevents tumor growth and induces apoptosis." (PMID 37242800, 2023). "Meanwhile, induction of the mitophagy pathway in tumor cells that lack STAT3 leads to enhanced antigen presentation for APCs and activation of T-cell." (PMID 36833401, 2023). "Increased IL-6/JAK/STAT3 signaling has been observed in different types of tumors and tumor infiltrating immune cells, as well as that this has been associated with lack of response to immunotherapy." (PMID 36720310, 2023). "Brassinosteroids, a plant antitoxin, were discovered to suppress PIAS3 and SOCS3 by inhibiting STAT3 signaling, which slowed tumor development." (PMID 37081874, 2023). "TGF-β has also been reported to silence miR-30a-5p through the STAT3/MALAT1 pathway in HNSCC favoring tumor growth." (PMID 37446353, 2023). "SUNb-PM not only facilitated the transformation of TAFs, collagen, and tumor vasculature but also induced tumor cell apoptosis, reducing tumor immune evasion by inhibiting the Stat3 and AKT signaling pathways." (PMID 38004600, 2023). "When values are lower than 0.35, it will shift to a three phenotypic hybrid with a completely pro-tumor behavior M2aM2cM2d, and when values are greater than 0.35 it will shift to an M2aM2d, inhibiting the action STAT3." (PMID 37283734, 2023). "Abnormally activated STAT3 signaling promotes tumor cell growth, proliferation, and survival, as well as tumor invasion, angiogenesis, and immunosuppression." (PMID 37240202, 2023). "Activated STAT3 signaling promotes the polarization of M2 TAMs to promote tumor progression, invasion, and migration." (PMID 37759870, 2023). "Exosomal miR-21 and IL-6 produced from CAFs together increased MDSC formation in oesophageal squamous cell carcinoma by activating STAT3, which made tumour cells resistant to cisplatin." (PMID 37569598, 2023). "This was associated with decreased S-palmitoylation and phosphorylation of STAT3 as well as HIF1α abundance in tumor lysates which is consistent with in vitro assay." (PMID 38051779, 2023).
tumor (continued). "While these data would be consistent with IL-23R pathway activation in tumor tissue, STAT3 activation can also be mediated by IL-6 or IL-10." (PMID 38375204, 2023). "The STAT3 transcription factor plays a critical role in the survival and proliferation of diverse tumor cell types, particularly MM." (PMID 37126127, 2023). "Noticeably, tumor tissues derived from STAT3-depleted HepG2 cells exhibited lower expression of STAT3 compared to those derived from HepG2 control cells." (PMID 36656267, 2023). "For example, OvCa tumor cells have been demonstrated to secrete exosomes containing miR-222-3p that polarize macrophages towards an M2 lineage via a SOCS3/STAT3 mechanism." (PMID 37173951, 2023). "Our in vivo experiments provided compelling evidence that deficiency in STAT3 R729me2a significantly curbed the metastatic potential of BRCA cells, thereby reinforcing the dependence of PRMT6-mediated tumor metastasis on STAT3 R729me2a." (PMID 37813837, 2023). "We find that metformin treatment of STAT3/AR-expressing PCa xenografts resulted in significantly reduced tumor growth accompanied by diminished mTORC1/CREB, AR and PSA levels." (PMID 37573301, 2023). "STAT1 shares very significant structural similarity with STAT3, but it has known effects on immune activation and tumor suppression." (PMID 39872303, 2023). "IL-6 is a TAM-produced cytokine that is involved in tumor progression and metastasis through the STAT3 signaling pathway and is responsible for the prosurvival adaptation of tumor cells to hypoxia." (PMID 36838713, 2023). "The number of mast cells in TEM also correlates with tumor grade, and their degranulation within the tumor leads to the release of chemokines and other tumor-promoting compounds such as CXCR4, STAT3 and serglycin which trigger further tumor progression." (PMID 38275375, 2023). "HBO can inhibit the hypoxia‐activated signal transducer and activator of transcription 3 (STAT3), slowing tumor growth and drug resistance." (PMID 36703877, 2023). "Previous study showed that Stat3 activation would promote the growth of blood vessels within the tumour hypoxic environment to provide more nutrients and oxygen." (PMID 37309689, 2023). "Butaselen, a TrxR1 inhibitor and ROS generator, suppresses PD-L1 expression on the tumor cell surface through the STAT3 pathway." (PMID 38136250, 2023). "Activation of the IL-6/JAK/STAT3 signaling pathway in cancer modulates the expression of several genes that drive the proliferation, metastasis, and survival of tumor cells while suppressing the antitumor immune response." (PMID 37511127, 2023). "Meanwhile, in tumor-infiltrating myeloid cells (TIMs), METTL3 mediates the m6A modification of JAK1 RNA and enhances the translation efficiency of the JAK1 protein, followed by the activation of STAT3 phosphorylation to promote tumor cell growth." (PMID 37996892, 2023). "This constitutively active JAK2 form, that hyperactivates the STAT3 phosphorylation, leads to upregulation of PD-L1 and to the immune escape of neoplasms." (PMID 36672229, 2023). "Further investigation demonstrated that arctiin suppresses inflammation, fibrosis, and tumor cell migration by inhibiting STAT3, TGF-β1, TLR4, NLRP3, VEGF, and cyclin D1." (PMID 37701157, 2023). "To validate the signaling changes were due to cytokine signaling, we stimulated tumor cells with GROα cytokine, and again observed increased phosphorylation of STAT3 and ERK1/2." (PMID 37423299, 2023). "Consistently, the eliminated macrophages, suppressing the function of STAT3 or chemokines and their receptors, significantly inhibited the tumor proliferation induced by adipocytes." (PMID 36593475, 2023). "It is becoming increasingly clear that cell-intrinsic inflammatory signaling in cancer cells with CIN can have tumor-promoting as well as tumor-suppressive effects mediated by STAT3 (and NF-κB) and STAT1 signaling, respectively." (PMID 37561163, 2023).